RNU6-953P (RNA, U6 small nuclear 953, pseudogene)
Gene: Small nuclear RNA gene on chromosome 15 (45,354,779 to 45,354,885, reverse strand). Ensembl gene ENSG00000238941.
Homologues: Orthologues: chimpanzee U6 (99% identical), macaque U6 (90% identical), pig U6 (86% identical), dog U6 (79% identical), guinea pig U6 (79% identical), mouse Gm22573 (77% identical), rabbit U6 (76% identical). Paralogues in human: RNU6-45P (91% identical), RNU6-12P (90% identical), RNU6-13P (90% identical), RNU6-16P (90% identical), RNU6-32P (90% identical), RNU6-1 (89% identical), RNU6-10P (89% identical), RNU6-17P (89% identical), RNU6-18P (89% identical), RNU6-2 (89% identical), RNU6-39P (89% identical), RNU6-3P (89% identical), and 1289 more.